ANKRD42 (ankyrin repeat domain 42)
Synonyms: FLJ37874; SARP; PPP1R79
Tractability: Antibody: the Human Protein Atlas places it where antibodies can reach. PROTAC: ubiquitination databases record sites on it.
Gene: Protein-coding gene on chromosome 11 (83,193,712 to 83,260,694, forward strand). Ensembl gene ENSG00000137494.
Subcellular location (Human Protein Atlas): Cytosol; Nucleoplasm; Plasma membrane
Gene Ontology:
Molecular function: cyclin-dependent protein serine/threonine kinase inhibitor activity; NF-kappaB binding
Cellular component: nucleus
Genetic constraint (gnomAD): Loss-of-function variants: 41 observed, 49.24 expected, observed/expected ratio (o/e) 0.83, 90% interval 0.65 to 1.08. The upper end of that interval is the gene's LOEUF score, 1.08, which puts it in group 4 of 6, group 1 being the genes least tolerant of losing a copy. Missense variants: 591 observed, 645.03 expected, observed/expected ratio (o/e) 0.92, 90% interval 0.86 to 0.98. Synonymous variants: 201 observed, 219.32 expected, observed/expected ratio (o/e) 0.92, 90% interval 0.82 to 1.03.
Homologues: Orthologues: chimpanzee ANKRD42 (99% identical), macaque ANKRD42 (92% identical), pig ANKRD42 (85% identical), rabbit ANKRD42 (84% identical), dog ANKRD42 (84% identical), guinea pig ANKRD42 (81% identical), mouse Ankrd42 (78% identical), rat Ankrd42 (78% identical), tropical clawed frog ankrd42 (59% identical). Paralogues in human: ANKRD37 (9% identical).